MMP2 (matrix metallopeptidase 2)
Diseases named in the same sentence as MMP2 in open-access papers (continued):
Sharing a sentence is not in itself a finding about the gene and the disease.
tumor (continued). "Therefore, researchers speculate that the mechanisms by which activated MMP-2 promotes tumor development is as follows: MMP-2 polarizes tumor-infiltrating lymphocytes toward a TH2 cell phenotype, which restrains the tumoricidal TH1-type response." (PMID 36776395, 2022). "Thus, THBS2 might promote cancer progression by remodeling the TME, affecting CD47-mediated signaling pathways, activating the pro-tumor functions of ADAMTSs, and enhancing MMP-2 expression." (PMID 35701829, 2022). "Driven by the current interest in multitarget approaches in cancer treatment, in the context of angiogenesis, we reasoned that by combining the inhibition of αvβ3 and MMP2 we could deliver a synergistic blockade of tumor cell migration, invasion and metastasis." (PMID 35209039, 2022). "Thus, the TmSm protein could be released in the tumor microenvironment through the MMP‐2 enzyme response and could be released into the cytoplasm through the TAT peptide." (PMID 35600646, 2022). "The collagenase MMP-2 is a prime example of how an individual member of the MMPs family contributes to cancer progression via a vast repertoire of extracellular matrix and non-extracellular matrix substrates, raising questions about its implication for every step of the tumor metastatic cascade." (PMID 35458618, 2022). "Additionally, the anti-angiogenic effect of quercetin has been closely linked to the decrease of VEGF-A, MMP2, and MMP9 expression, as well as to the inhibition of both tumor growth and angiogenesis by targeting VEGFR2 regulated by AKT/mTOR/P70S6K signaling pathway." (PMID 35204240, 2022). "Interestingly, strong MMP-2 expression was observed in tumor vasculature and stromal cells." (PMID 35457074, 2022). "Examining the roles of MT1-MMP and MMP-2 within the nucleus and how they potentially interact may provide new insights into the roles of nuclear MMPs critical in regulating cancer epigenetics and tumor migration and invasion." (PMID 36076910, 2022). "ATO may reduce various tumor cell activities, inhibit cell attachment to peritoneal mesothelial cells, enhance the interaction between tumor cells, downregulate the expression level of matrix metalloproteinase (MMP)-2 and MMP-9, and upregulate the expression level of MMP inhibitor (TIMP)." (PMID 36090905, 2022). "In addition, the expression of MMP2 was found to be higher in the margins of cancer tissues, which may be related to the tumor infiltration." (PMID 34976953, 2021). "Similarly, other studies confirmed that the activity of MMP-2 might be associated with the tumour stage, while mRNA expression of MMP-9 was evaluated in regard to tumour recurrence." (PMID 33923108, 2021). "Moreover, CD97 and SMYD3 promote tumor progression by regulating MMP2." (PMID 34007838, 2021). "The mechanism could be that it downregulates the expression of MMP-2 and Her-2 proteins, enhances intracellular calcium channel signals, eliminates the correlation of mitochondrial membrane potential, and thus inhibits the metastasis of malignant tumor cells." (PMID 35115937, 2021). "However, MMP2 released by tumor cells may directly affect APCs or other cells within the TME that express TLR2 and TLR4." (PMID 34032639, 2021). "Moreover, also in cancer tissues, the expression of MMP2 in marginal sites was significantly higher than that in central sites, indicating that the expression of MMP2 may be related to the tumor invasion." (PMID 34976953, 2021). "Furthermore, our ELISA data indicated that the increased VEGFA, MMP2, and MMP-9 levels upon BATF2 downregulation were significantly impaired after AMD3100 injection, suggesting that these tumour-promoting cytokines associated with MDSCs were also blocked by AMD3100." (PMID 33452462, 2021). "Moreover, Mmp2 OE skews priming of tumor antigen-specific T cells toward a Th2 phenotype." (PMID 34032639, 2021). "Furthermore, um-PEA reduced tumor cell migration by reducing MMP2 and TIMP1 expression." (PMID 33923494, 2021).
tumor (continued). "Although MMP-9 and MMP-2 are mostly similar substrates, it is hypothesized that they are regulated by different mediators, expressed under different conditions, and therefore have different instances in which they affect the tumor micro-environment." (PMID 32172480, 2021). "Furthermore, VEGF is an important angiogenic factor and MMP2/9 are crucial for tumor cell motility." (PMID 34026596, 2021). "AKT was reported to promote the activity of NFκB, known to regulate the transcription of matrix metalloproteinases, MMP2/9, members of the large family of MMPs, a group of Zn2+-dependent endopeptidases involved in degradation of extracellular matrix components and tumor progression." (PMID 34209215, 2021). "Specifically, MMP-2-catalyzed cleavage of fibronectin (FN) and vitronectin (VN) allows generation of proteolytic fragments with enhanced adhesive properties and may be involved in tumor cell–mesothelial cell adhesion to initiate metastases." (PMID 33810259, 2021). "However, under the catalysis of MMP-2, the created peptide nanoparticles could transform into nanofibers, which enhanced the relaxivity and retention of created contrast agent in tumor region and promoted the MRI of tumors." (PMID 34425823, 2021). "However, the prognostic characteristics of MMP-2 expression in tumor patients remain controversial." (PMID 34027107, 2021). "Furthermore, CypA knockdown activated caspase-3, a critical executioner of apoptosis, and suppressed the expression of matrix metalloproteinase (MMP)-9 and MMP-2 that play an important role in tumor invasion and metastasis, consistent with the effect of compound 9 treatment in our previous study." (PMID 33804393, 2021). "Moreover, reduced MMP-2 release from cancer-associated fibroblasts after treatment with WIN 55-212.2 led to reduced invasion of prostate cancer cells, suggesting that cannabinoids inhibit invasion not only by direct action on tumour cells." (PMID 34830856, 2021). "Similarly, a high number of tumor-associated macrophages lead to an increased production of angiogenic factors such as VEGF, PDGF, IL-8, TNF-α und bFGF and an enhanced expression of angiogenesis promoting enzymes such as MMP-2, MMP-7, MMP-9 and MMP-12." (PMID 34821752, 2021). "According to studies, increased expression of SPARC might lead to activation and subsequent phosphorylation of ERK1/2, with p-ERK regulating the transcription of MMP-2/9, thus promoting cell growth and proteolysis of extracellular matrix related to tumor invasion." (PMID 32670867, 2020). "Moreover, MMP-2 plays an role in the migration and invasion of tumor cells." (PMID 33330466, 2020). "In addition to IL27, IL10 also negatively affects proangiogenic cells in the tumor microenvironment, such as activated macrophages, by inhibiting proangiogenic MMP2 and upregulating TIMP 1 and thereby suppressing the process of angiogenesis during PCa progression." (PMID 32842503, 2020). "It is known that aspirin leads to cell apoptosis by inhibiting Bcl-2 expression and downregulating COX-2 expression, which is known to convert arachidonic acid to prostaglandins, and it may reduce tumor-cell invasion through the downregulation of MMP-2 expression." (PMID 32000828, 2020). "For instance, the 100 nm nanoparticles could be reduced to 10 nm by responding to proteases (i.e., MMP-2) in tumor microenvironment, which effectively enhanced the diffusion of drugs into the tumor's dense collagen matrix, while maintained long circulation for achieving EPR effect." (PMID 32292515, 2020). "Therefore, KDELC2 expression could activate tumor migration and invasion by upregulating MMP2 expression in GBMs." (PMID 32927743, 2020). "However, the presence of AR in the positive MMP-2 in tumor epithelium reduced survival in patients." (PMID 32718331, 2020).
tumor (continued). "Additionally, the results showed that CA reduces the level of MMP2 in the tumor cell lysate by 42.89% (CA, 40 mg/kg) or 49.87% (CA, 80 mg/kg), respectively, and in ascites fluid by 55.62% (CA, 40 mg/kg) or 78.23% (CA, 80 mg/kg) compared to the saline-treated control group." (PMID 33261130, 2020). "More importantly, SB-3CT targets MMP2/9 in the tumor microenvironment rather target immune response directly, which is how antibodies function, and it may cause less toxicity or immune-related adverse events, thus making SB-3CT a potential reagent for future immunotherapy." (PMID 32988398, 2020). "Our results also showed that CGA inhibited HepG2 cell proliferation and HCC growth by inactivation of ERK and down-regulation of MMP-2/9, which prevented the degradation of the extracellular matrix; thus, these mechanisms may be involved in its anti-tumor effect." (PMID 32655395, 2020). "Thus, since in this emerging MT1-MMP/MMP-2 cascade, the secretion rate of MT1-MMP correlates directly with the amount of MMP-2 molecules, we obtain therefore that the presence of the ECM fibres enhances the production of the MMP-2 molecules that are then released at the tumour boundary." (PMID 32458057, 2020). "Finally, other regulatory mechanisms of MMP-9 expression are mediated by MMP-9 allelic variation (rs3918251GG (A>G) and by the over-expression of SOX4 responsible for the concomitant up-regulation of MMP-2/9 and NF-κB/p65 and, consequently, for a more aggressive tumor phenotype." (PMID 32392801, 2020). "Furthermore, growth factor inhibitors such as IL-6 inhibitors (tocilizumab) and MMP-2/-9 inhibitors (β-d mannuronic acid) have been designed to affect tumor progression, invasion, and metastasis by inhibition of chronic immune response and prevention of remodeling ECM." (PMID 32370233, 2020). "In head and neck SCC tissues, MMP-2 and FAK transcript levels directly correlated with each other and with EMT genes, but only perturbed MMP-2 gene expression was associated with poor outcome independently on FAK expression, the EMT transcriptional phenotype, size of the tumor or disease stage." (PMID 33321813, 2020). "Furthermore, overexpression of MMP-2 negated the effect of Porf-2 in tumor cell migration." (PMID 32676454, 2020). "In addition, induction of type A lactate dehydrogenase (LDH-A), regulating the transforming growth factor-β2 (TGF-β2), has been shown to trigger the cascade of transcriptional regulation of MMP-2 and integrin αvβ3 expression, strongly influencing the tumor invasiveness." (PMID 33020459, 2020). "Moreover, we indicated that serum levels of MMP-2 and classical tumor markers were lower, whereas TIMP-2 concentrations – higher in PC who alive in comparison to those who died because of PC, however the significant difference was found only for CEA concentrations (p = 0.004)." (PMID 30719232, 2019). "However, in support of a true anti-tumorigenic role, the same group found an inverse correlation between “true” Tregs at the invasive front of urothelial cancers and the expression of matrix metalloproteinase 2 (MMP2) which is produced by tumor cells and macrophages and promotes tumor invasion." (PMID 31824850, 2019). "MMPs, such as MMP-2 and MMP-9, consist of a multigene family of zinc-dependent ECM-remodeling endopeptidases that accelerates proteolytic degradation of ECM and thereby causes migration and invasion of cancer cells, which in turn results in the promotion of tumor metastasis." (PMID 31391858, 2019). "Finally, we checked the expression level of MMP2 in tumor tissues by western blot analysis." (PMID 31263239, 2019). "In addition, increased expression of MMP2 may contribute to the remodeling of the tumor microenvironment in GC." (PMID 30568862, 2018). "Moreover, TIMP-3 suppresses tumor angiogenesis in MMP-2-downregulated lung cancer." (PMID 29467412, 2018). "Moreover, MMP-2 and MMP-9 have been associated with tumor progression and decreased survival." (PMID 29713337, 2018).
tumor (continued). "Besides, a possible explanation for the role played by KiSS1 in cancer biology can be extrapolated from the correlation between KiSS1 and matrix metalloproteases (MMPs), particularly MMP-9 and MMP-2, whose significance in tumor invasion and metastasis formation is well known." (PMID 29721201, 2018). "MMP2 is responsible for extracellular matrix (ECM) digestion and VEGF proteolytic release from the tumour matrix 26, 36; therefore, the reduced expression of MMP2 found in AQP1 KD tumours might also reduce the amount of the available VEGF necessary to induce a normal level of tumour angiogenesis." (PMID 29044946, 2018). "Moreover, ETV5 has been shown to co-localize with MMP-2 and -9 at the invasive front of the tumor." (PMID 29682175, 2018). "Further studies showed that the anti‐tumour effects of gartanin might involve cell cycle arrest in G1, increased protein expression level of p27Kip1, suppressed protein expression level of cyclin D1 and inhibited secretion and activity of MMP‐2/‐9." (PMID 27491646, 2017). "Therefore, based on these data, we hypothesized that propoxur could reduce tumor cell migration and invasion through ROS-dependent secretion and activation of MMP-2 and MMP-9." (PMID 29152067, 2017). "In addition, TM-601 alone, similar to native CTX, could inhibit or kill the tumor cells and reduce angiogenesis due to its ability to bind to and inhibit MMP-2, contributing to the antineoplasic effect of I131-TM-601." (PMID 30873475, 2017). "Furthermore, tumor cells recruit MMP-2- and MMP-9-producing neutrophils and macrophages." (PMID 29112161, 2017). "Interestingly, hMDA-7 was shown to suppress tumor cell invasion and migration by down regulating MMP-2, MMP-9, and VEGF expression, although the detailed mechanisms remain unclear." (PMID 28985230, 2017). "However, it significant correlation was found only between ERβ and MMP-2 in tumor tissues." (PMID 28915603, 2017). "The protease MMP-2 is not typically associated with tumor invasion but it is indicated that integrin-mediated EGFR signaling is activated through the direct binding of MMP-2 and PAK4 (a serine/threonine kinase that is involved in the regulation of cell motility, invasion, and growth)." (PMID 28629170, 2017). "Wip1 and MMP-2 immunohistochemical stainings in the Wip1-shRNA tumors were remarkably lower than that in control, indicating that interference for Wip1 may restrain the proliferation of tumor cells through MMP-2." (PMID 28915621, 2017). "In addition, MMP-2 and MMP-9 have been linked to tumor cells migratory and invasive ability." (PMID 28548944, 2017). "Some authors have not found an association of MMP-2 (-1306 C/T) polymorphism with tumours." (PMID 27051552, 2016). "Furthermore, ETSP from expression of EFEMP1 variant construct E5 would have gained tumor-suppression function in SITC by targeting NOTCH signaling and MMP2-related oncogenic activities and the corresponding function in tumor invasion and cancer stem cell phenotypes." (PMID 27713911, 2016). "In turn, the overexpression of MMP-2 mRNA in tissues surrounding nodular BCCs may a kind of counterbalance effect: cancer cells from the collagen-entrapped tumor may stimulate the synthesis of MMP-2 in normal adjacent cells, e.g. acting via the EMMPRIM protein." (PMID 27406386, 2016). "Increased expression of MMP-2 is found in the stroma of squamous cell carcinoma compared with that of basal cell carcinoma and may thus be responsible for the different pattern of invasion found in these two tumours." (PMID 26850723, 2016). "In the present study, we used cell and animal models to test the possibility that stabilization of Bcl-2 protein by phosphorylation at Serine 87 by PXN-mediated ERK activation may be responsible for tumor progression and metastasis via upregulation of MMP2 expression." (PMID 25826088, 2015). "Furthermore, radiation enhanced MMP-2 activity and increased tumor margin invasiveness in vivo." (PMID 26245666, 2015).
tumor (continued). "However despite the multiple attempts at imaging MMP-2/9, it is unclear whether imaging these molecules offers any potential clinical advantage in detecting smaller tumor sizes than commercial Gd chelates." (PMID 26336058, 2015). "Here we have taken the first step toward answering that question by injecting MMP-2/-9 producing tumor cells or control saline into the mammary fatpads of mice and determining whether the ACPPD-Gd agent offers an advantage over commercial Gd chelates for detecting tumors of varying sizes." (PMID 26336058, 2015). "Thus, the communication between adipocytes and tumor cells may be responsible for the activation of MMP-2 in tumor cells and may durably permit the successful colonization of a wider area at the tumor edge." (PMID 25747684, 2015). "An increase in Bcl-2 expression may promote tumor invasion via increased MMP2 expression." (PMID 25826088, 2015). "Interestingly, fucoidan can reduce the tumor-induced VEGF expression as well as the expression of MMP-2, MMP-9 and NF-κB in lung tissues, suggesting fucoidan restrains cancer cells from invasion and metastasis through suppressing epithelial cell proliferation and blood vessel formation." (PMID 25854641, 2015). "Also, JWA suppresses tumor angiogenesis via Sp1-activated MMP-2 in human gastric cancer." (PMID 26046674, 2015). "However, expressions of angiogenesis-related genes such as HIF1α, VEGF and tumor invasion-related genes like MMP2, MMP9, E-cadherin and β-catenin were increased by either carbon ion beam or X-ray irradiation alone and/or in combination with gemcitabine compared to." (PMID 25849939, 2015). "In addition, the protein expression of MMP-2 was significantly reduced, suggesting that CDX2 suppressed the invasion and metastasis of tumor cells, possibly by downregulating the expression of MMP-2, which was also demonstrated in the results of our previous in vitro investigation." (PMID 26005051, 2015). "LOX cross-linking collagen IV in the basement membrane was essential for recruitment of CD11b+ myeloid cells, which could secrete MMP-2 to resolve collagen to enhance the tumor invasion and recruitment of BMDCs and metastasizing tumor cells to pre-metastatic niche." (PMID 24587996, 2014). "RECK may reduce tumor progression through functionally downregulating MMP-2 expression." (PMID 24765174, 2014). "Therefore, MMP-2 is a potential target for metastatic tumor imaging." (PMID 25547485, 2014). "For instance, in genetically-engineered mice, although the lack of MMP-2, -7, or -9 in CR2-Tag mice all led to reduced tumor vascularity, the loss of MMP-2 conferred decreased lung metastasis and increased survival, while the lack of MMP-9 led to increased perivascular invasion." (PMID 24978435, 2014). "MDAPCV could be generated in the tumor as a result of MDAP3000 cleavage by MMP-2." (PMID 25010662, 2014). "We investigated whether the mRNA expression of IL-6 in the control tumor xenografts had any correlation with the mRNA levels of invasion-associated genes such as CXCR4, MMP-2, and MMP-9 in response to systemic administration of paclitaxel and oral gavages of CYT387." (PMID 24782986, 2014). "However, the roles of MMP9 and MMP2 in the heightened invasion upon anti-angiogenic therapy might be only one force behind this phenomenon, and TEMs could secrete other tumor-remodeling molecules that contribute to the adaptive response." (PMID 24809734, 2014). "In addition, to assess whether downregulation of pro-MMP-9, pro-MMP-2, uPA expression in serum-free tumor conditioned medium affects the degradation of the extracellular matrix, radiolabeled type IV collagen degradation assay was performed." (PMID 25176506, 2014). "Alternatively, tumor-derived MMP2 may prime DC for Th2 cytokine response." (PMID 24204708, 2013). "Therefore, the inhibition of the ERK1/2 signaling pathways may result in a reduced expression of MMP-2, and reduced tumor cell migration." (PMID 24278338, 2013).